CD44 (CD44 molecule (IN blood group))
Diseases named in the same sentence as CD44 in open-access papers (continued):
Sharing a sentence is not in itself a finding about the gene and the disease.
cancer (continued). "With increasing evidence supporting the existence of cancer stem-like cells (CSCs), pancreatic CSC populations have recently been identified based on cell membrane marker CD44+/ESA+ /CD24+ cells and CD133+ cells." (PMID 25849939, 2015). "The cellular membrane protein CD44 is an important cancer stem cell (CSC) marker and plays a critical role in many cancers' distant metastatic potential as well as AML stem cell homing to the bone marrow niche." (PMID 26079538, 2015). "CD44+/CD24− cells have stem cell-like properties and were used here as a marker of the cancer stem cell-like population." (PMID 26016502, 2015). "In this review, we discuss the nature of such interactions and the important therapeutics that can target CD44 and RHAMM in inflammation and cancer." (PMID 25999946, 2015). "In order to further determine the effects of SATB1 expression on the cancer stem cell population, the effects of SATB1 overexpression in MCF-7 cells and SATB1 knockdown in BT-549 cells on CD44+/CD24− populations were investigated." (PMID 25586771, 2015). "In this study, to determine the importance of HA/CD44 in TGF-β1-induced EGF signaling activation and EMT in cancer cells, we used the HAS inhibitor, 4-MU, to block HAS expression and shRNA targeting CD44 to knockdown CD44 expression." (PMID 26005723, 2015). "CD44 and CD133, which have been described to correlate with a cancer stem cell and drug resistance phenotype, showed enrichment in only one of the four models." (PMID 26607327, 2015). "To begin to understand the ability of marker combinations to select for cancer stem cells, we FACS-sorted the UM-HMC-3A and UM-HMC-3B cell lines according to ALDH activity, CD10, CD24, and/or CD44 protein expression." (PMID 26449187, 2015). "Taken together, these results suggest that CD44 functions as an upstream regulator of ERK, AKT and Hippo-YAP pathways and contributes to the failure of cell contact inhibition in cancer cells." (PMID 25605020, 2015). "To quantify the effect of therapy on the fraction of cancer stem cells in vivo, we digested the xenograft tumors, generated single-cell suspensions, stained them for ALDH activity and CD44 expression, and sorted ALDHhighCD44high cells by flow cytometry." (PMID 26287605, 2015). "Therefore, targeting CD44+ cancer stem like cell may decrease PCa EMT and metastasis." (PMID 25483103, 2015). "These zones also show parallel alternating levels and/or subcellular localization of multiple cancer stem/progenitor cell (CSC) markers, including β-catenin/CTNNB1, ALDH1, and CD44." (PMID 26098881, 2015). "The mRNA levels of cancer stem-related genes (CD133, CD44), EMT-related markers (N-cadherin, vimentin and E-cadherin) and transcriptional factors (Snail, Slug and Twist) were detected under different experimental conditions." (PMID 26452130, 2015). "CD44 is a membrane receptor for hyaluronic acid and works in process of epithelial-to-mesenchymal transition (EMT) and assembly of stem cell niches in cancer." (PMID 26572077, 2015). "To further characterize these sphere-forming cells, we examined the presence of two common cancer stem cell surface markers: CD24 and CD44." (PMID 25011053, 2015). "Several genes, such as CD44, KLF5, K-Ras and hexokinase 2, have been confirmed as the direct targets of miR-143 in cancer cells." (PMID 26484567, 2015). "CD44 is an adhesion protein, capable of binding to the ECM and a proposed stem cell marker in several types of cancers." (PMID 25991672, 2015). "The CD24+CD44+ESA+ cells, which was also documented to be with characteristics of cancer stem cells, didn’t show high capacity to resist gemcitabine." (PMID 26391180, 2015).
cancer (continued). "ADAM10 is a sheddase that cleaves ectodomains of transmembrane proteins such as E-cadherins, N-cadherins, Notch, CD44 and amyloid precursor protein (APP), which play a significant role in proliferation, migration, invasion or stemness of cancer cells." (PMID 26440150, 2015). "The qRT-PCR analysis normalized to the LDHA internal house-keeping gene control expression showed a statistically significant reduction in CD44 expression of liposomal CDF treated tumors, confirming the effect of CDF on CD44hi expressing cancer stem cells." (PMID 26098778, 2015). "In these studies, sol-CD44 blocks HA-activated CD44 clustering and inhibits CD44-mediated recruitment of activated MMP-9 and invasion potential of cancer cells." (PMID 25999946, 2015). "Shk also reduced the mRNA expression of CSC markers in CD44+ CD24− cells and patient derived primary cancer cells." (PMID 25973915, 2015). "Here, we used cell lines and xenograft models recently generated in our laboratory to screen for cancer stem cells using several combinations of ALDH, CD44, CD24, and CD10 markers." (PMID 26449187, 2015). "They express specific cell-surface markers such as CD133, CD44 and EpCAM; these markers can be used to isolate CSC population from primary tumors and established cancer cell lines." (PMID 26506419, 2015). "CD44, which is a cell adhesion molecule (CAM), is the most studied HA receptor in cancer research and is commonly found on the cell surface of epithelial, hematopoietic and neuronal cells." (PMID 25706756, 2015). "While ALDH can be used as an independent marker for cancer stem cells in other cancer types, we have demonstrated that a two-marker combination of ALDH and CD44 is necessary to enrich for this aggressive cancer stem cell phenotype." (PMID 26449187, 2015). "In the simulations, we focused only on CD44, CD47 and MET overexpressions and underexpressions (excluding EPCAM) because we are considering the cancer cells that are already in the blood vessels." (PMID 25978366, 2015). "Beside modifying ECM proteins interactions, extracellular TG2 was found to activate nuclear factor-kappa B (NF-κB) signaling, leading to CD44 up-regulation and EMT activation, contributing to increased cancer cell invasiveness and peritoneal dissemination." (PMID 25170871, 2014). "CD44 and c-MET collaboration, and their interactions on the plasma membrane, lead to the activation of downstream signaling pathways that promote cancer progression." (PMID 24823486, 2014). "Cancer stem cell markers of SP cells, OCUM-12/SP and OCUM-2MD3/SP, such as CD44, CD133, and NANOG, were analyzed by RT-PCR." (PMID 25379943, 2014). "CD44 and MMP9 have previously been shown to form a complex and together promote invasiveness in cancer cells." (PMID 25184276, 2014). "Breast CICs can be characterized by increased expression of CD44 and decreased expression of CD24 (CD44↑/CD24↓) compared to the remaining cancer cells which are referred to as the bulk cancer cells (BCs)." (PMID 25051360, 2014). "Cancer stem cell immunophenotype studies in oral squamous cell carcinoma indicated that patients with CD24 and CD44 double-positive cells showed the lowest overall survival rate compared to other immunophenotypes." (PMID 24612587, 2014). "CD44 is involved in cell-to-cell and cell-to-matrix interactions and has been used as a CSC marker in cancers of the head and neck, breast and prostate." (PMID 25240521, 2014). "Connecting the deregulation of the BCSCs markers (CD44, CD24) to a possible selection of a more aggressive cancer phenotype by the chemotherapy Regimen 2, basically by the addition of taxanes, is an appealing scenario." (PMID 24632568, 2014). "We observed that the protein expression of the TAM markers CD68 and CD163 as well as the cancer stem cell (CSC) markers ALDH1, CD44, and SOX2 increased successively from the normal oral mucosa to OSCC." (PMID 24883329, 2014).
cancer (continued). "Lymph node metastatic OTSCC, express higher CD44/CD24 levels, produce cancer cell spheres in larger number and rapidly (24 hours) compared to node negative OTSCC (1 week) and non-cancer specimens (3 weeks)." (PMID 25685059, 2014). "The expression of several cancer metastasis-related genes such as ADAM9, CDH9 and CD44 was increased following miR-182 knockdown." (PMID 24519909, 2014). "Six SNPs of CD44 were analyzed using a real-time polymerase chain reaction (PCR) in 203 patients with HCC and in 561 cancer-free controls." (PMID 24971320, 2014). "Cancer stem-like cells can be enriched by collecting cells expressing CSC markers such as CD133 and CD44." (PMID 25228591, 2014). "Since more than 99% of SUM159 cells were CD44+ cells in both monolayer and sphere cultures, we utilized CD24 and EpCAM as additional surface markers to further investigate cancer stem cells." (PMID 25229616, 2014). "Most cancer stem cell assays have thus far depended on a variety of different cell surface markers, including CD133, CD44, CD166, and CD24." (PMID 24489842, 2014). "TFN1, CD44, and MMP2 are all EMT markers genes, whose aberrant expressions were involved in the EMT of cancer." (PMID 24402783, 2014). "CD44 is a primary receptor for HA, a major component of the ECM, and it plays a critical role in cell signaling and cell-ECM interactions in cancer." (PMID 24403253, 2013). "Many of these isoforms (including CD44, ENAH, p120-Catenin, EPB41L5) show direct correlation with both MET-EMT and metastasis, in multiple cancer types." (PMID 24124593, 2013). "Although the pathways of the stem cell differentiation remain unknown, the expression of CD44 in our 3D culture suggests that the complex structure of scaffolds and the close communication of neighboring cells encouraged the differentiation of cancer stem cells." (PMID 24101930, 2013). "MCSCs possessed the high expression of cancer stem cell markers (CD133, CD44, OCT4, NANOG, and ABCG2) and the ability of differentiation." (PMID 24188098, 2013). "CD133 and CD44 have also been recognized as HpSCs biomarkers and CD133- and CD44-positive cells represented cancer stem cells in HCC." (PMID 23192764, 2013). "The expression of CD44 and CD133 were studied by flow cytometry and the gene expressions of pluripotency factors were studied by qPCR to demonstrate the enrichment of cancer stem cells (CSCs) in SorR cells." (PMID 24244338, 2013). "Isolated CD44 and CD133 cancer cells also express stem cell regulators Oct4, Sox2, nanog, and nestin." (PMID 24160469, 2013). "For cancers of breast, pancreas, prostate, head and neck and colon, the T-ISC phenotype consistently includes surface CD44+ expression." (PMID 23982961, 2013). "A population of CTCs from patients with primary luminal cancer (expressing EPCAM, CD44, CD47 and MET) generated multi-site metastases when injected into mice." (PMID 24286369, 2013). "CD44 and CD133 are commonly used as cell surface markers representing the cancer stem cells (CSCs) subpopulation in HCC." (PMID 24244338, 2013). "We analysed the expression of markers for cancer stem cells, CD24 and CD44 by flow cytometry and real time PCR." (PMID 24391839, 2013). "In breast cancer, the stem cell population is CD44+/CD24-, and CD133 marks cancer stem cells in brain tumors, colorectal carcinoma, and pancreatic carcinoma." (PMID 24376802, 2013). "For example, in breast cancer, repression of ESRP results in a switch in CD44 isoform expression that is critical in the induction of EMT and cancer progression." (PMID 24124593, 2013). "The patients with the features of both MBC and basal-like cancers had enrichment for stem cell-like markers with an elevation of CD29/CD24 and CD44/CD24 ratios." (PMID 23738706, 2013). "Through the engagement of specific integrin receptors or CD44, OPN exerts its pleiotropic function in cancer cell survival, ECM remodelling, cell migration, and metastasis in solid cancers as well as in aggressive B-cell lymphomas." (PMID 22400028, 2012).
cancer (continued). "Owing to current contradictions, we herein review recent literature and discuss the importance of CD44 and CD24, as potential surface markers in identification and isolation of CSC, in different cancers." (PMID 22693526, 2012). "To investigate the efficiency of ARR in inhibiting the growth of cancer stem cells, we examined the inhibition of sphere formation in CD44+/CD24+/EpCAM+ and CD133+ cancer stem cells." (PMID 22570653, 2012). "Recent investigations found that CD24 is coexisting with CD44, CD29, and CD31 in various cancers and gained new interest as a CSC marker." (PMID 22693526, 2012). "The variations in CD44 and CD24 proportions from cell line to cell line show the phenotypic heterogeneity in different cancer types." (PMID 22693526, 2012). "We found that the levels of CD44 and CD24 expression show great variation between cell lines even in cells of the same cancer subtype." (PMID 22693526, 2012). "Among up-regulated miRNAs, miR-330 regulates CD44 and CDC42 and thus modulates tumourigenesis and angiogenesis in cancer." (PMID 22050707, 2012). "In view of the roles of PDGF, fibrin(ogen) and CD44 in cancer metastasis, we aimed to delineate the effect of PDGF on CD44-fibrin recognition." (PMID 23056168, 2012). "Using flow cytometry, we studied the individual expression of EpCAM, CD44, CD24 and ABCG2 and also studied the co-expression of EpCAM with other three putative cancer stem cell markers." (PMID 22328825, 2012). "Both CD44 and CD24 are known to contribute to cellular signaling and cell adhesion, and their role in cancer recurrence has been investigated." (PMID 22839505, 2012). "We mainly focus on analysing the significance of CD44 and CD24 as CSC surface markers in combination or with other putative markers in different types of cancer." (PMID 22693526, 2012). "In cancer cells, RHAMM has been shown to bind CD44 on the cell surface, and HA binding to this complex promotes downstream signaling resulting in Rho GTPase activation and increased cell migration." (PMID 23166824, 2012). "The impairment of SNO homeostasis also expanded a cancer stem cell-like subpopulation in MCF-7 cells, as indicated by the increase of percentage of CD44+ cells and the augmented capability to form mammospheres in vitro." (PMID 23216744, 2012). "Cells with mesenchymal-like morphology deriving from normal and cancer tissues showed similar levels of CD14, CD29, CD36, CD44, CD45, CD49e, CD73, CDw90, CK18, FLT-1, STRO-1, SH4, HLA-ABC, and integrin α2β1 expression." (PMID 22330345, 2012). "RHAMM can also bind directly to CD44 at the plasma membrane, and activate CD44 signaling through ERK1/2, potentially enhancing cancer cell migration, and indicating the collaboration of different receptors to activate signaling pathways." (PMID 24213471, 2012). "For example, HA-mediated mitogenic signalling has been suggested to involve an interaction between CD44 and erbB family members whilst the v6 isoform (‘CD44v6’) is critically required for HGF/SF-mediated c-Met activation in human cancer cells." (PMID 23039365, 2012). "Anti-CD44 treatment induces apoptosis in CD90-positive cells and thus CD44 plays an important role in the survival of cancer cells." (PMID 22187659, 2011). "We also found that the cancer stem cell-like traits, such as tumorsphere formation, expression of ALDH1 and CD44, were significantly elevated in Twist-overexpressing cells." (PMID 21284870, 2011). "A multipotent, tumorigenic E/M cell subset (E/M-MP), that fits the profile of true cancer stem cells, had high levels of cytoplasmic E-cadherin, membrane CD133 and membrane CD44." (PMID 21264259, 2011). "In our study, we show that B6TC cells express a high level of CD44+ and a low level of CD24−, a phenotype similar to the cancer stem cells." (PMID 21673810, 2011).
cancer (continued). "Earlier studies have observed individual roles for CD44 and COX in embryogenesis, angiogenesis, cellular proliferation, wound healing, as well as in pathophysiological conditions, such as cancer and inflammation." (PMID 21819617, 2011). "CD44 and CK18 are highly expressed in cancer stem cells and function as tools for their identification and characterization." (PMID 21904548, 2011). "Cancer stem cells express numerous universal markers such as CD133, CD44, CD24, ESA and ALDH1 in different cancers." (PMID 21521521, 2011). "CD44 is involved in cell–cell and cell–matrix interactions and has been used as a CSC marker in leukaemia and cancers of the pancreas, breast, prostate and head and neck." (PMID 21829201, 2011). "The aims of this work were therefore to evaluate the expression of CD44, Musashi-1 and CD133 at different steps in the Correa pathway of GC and to determine their prognostic and predictive significance in this cancer type." (PMID 21829201, 2011). "Therefore, CD90+CD44+ subpopulations might be the migrating cancer stem cells of liver cancer." (PMID 21542915, 2011). "Stem/progenitor cell populations for many types of cancer, including HCC, are thought to be enriched with cells that express CD44, a receptor for the stem cell growth factor, osteopontin." (PMID 21912653, 2011). "CD133 is much more restricted in expression compared with other CSC markers such as CD44 and ALDH, which are more universally expressed in normal as well as cancer cells." (PMID 21317983, 2011). "Their study demonstrates that only a small subset of CD44+/CD24− breast cancer cells is capable of driving carcinogenesis and possesses the ability to self-renew and to generate multiple cancer cell types." (PMID 22174624, 2011). "A recent report also showed that high expression of CD44v6, a CD44 isoform, was detected more frequently in SCC than in other carcinoma types." (PMID 21819617, 2011). "Previous studies indicate that both CD44 and HA are involved in chemotherapeutic drug resistance in many cancer types, but regulation of MDR by CD147 and CD44 in CaP remains to be fully defined." (PMID 20736947, 2010). "Both PAR2 and PAR1 activation resulted in up-regulated expression of several genes (CD44, FOSL1, TNFRSF12A, RAB3A, COPEB, CORO1C, THBS1, SDC4) known to be important in cancer." (PMID 21072196, 2010). "Such tumors display a stem cell-like gene expression profile, including the over-expression of cancer stem cells (CSCs) markers, such as CD133 and CD44." (PMID 21092249, 2010). "On the other hand, in the EUS-FNA samples, the gene, CDK2A, CD44, S100A4 and MUC1 were specifically related to the 2nd clustering between cancer and non-cancer (p < 0.05)." (PMID 20416107, 2010). "Immunofluorescence labelling results of EOC cells with uPA, CD44, MDR1 and MRP2 antibodies showed positive staining in all cancer cell lines." (PMID 19603017, 2009). "Among selected genes, CD24, CD44, and CD74 are cell surface adhesion molecules shown to be over expressed in various cancers." (PMID 19602232, 2009). "The CD44-MAPK-PI3K signaling leads to uncontrolled expression of uPA/uPAR and MDR1, which promotes invasive and multi-drug resistant cancer cell phenotype." (PMID 17327908, 2007). "The uPAR-positive cells in all SCLC lines demonstrated multi-drug resistance, high clonogenic activity and co-expression of CD44 and MDR1, putative cancer stem cell markers." (PMID 17327908, 2007). "In summary, these results indicate that hepatic Mif knockdown may result in improved hepatic immune microenvironment, reduced cancer stemness and adhesion in MASLD, which was partially dependent on CD44." (PMID 41545340, 2026).